MFAP4 (microfibril associated protein 4)
Diseases named in the same sentence as MFAP4 in open-access papers (continued):
Sharing a sentence is not in itself a finding about the gene and the disease.
glioma (continued). "In this study, MFAP4 was identified as a potential biomarker for prognosis and immunotherapy in glioma patients by bioinformatics analysis." (PMID 40061958, 2025). "In the TCGA dataset, MFAP4 expression was also significantly associated with DSS and PFI in glioma patients." (PMID 40061958, 2025). "Glioma infiltration of 24 immune cell types was detected using ssGSEA and its correlation with MFAP4 levels was assessed by Spearman’s correlation coefficient." (PMID 40061958, 2025). "By analyzing different datasets, we found that MFAP4 was aberrantly overexpressed in gliomas and correlated with poor clinicopathological features of gliomas." (PMID 40061958, 2025). "Logistic regression, Lasso analysis, Receiver Operating Characteristic (ROC), Kaplan-Meier analysis, and Nomogram modeling assessed the correlation between MFAP4 and clinicopathological features of gliomas." (PMID 40061958, 2025). "Firstly, conduct in vitro and in vivo experiments to elucidate the specific mechanism of MFAP4 in glioma cell proliferation, migration, and invasion." (PMID 40061958, 2025). "COL3A1 has been shown to be associated with poor prognosis and drug resistance in GBM patients, so we mainly focused on whether MFAP4 plays an important role in the development of gliomas." (PMID 40061958, 2025). "MFAP4 has relevance in regulating both tumor immunity and iron death, and cellular function assays have demonstrated that MFAP4 promotes the proliferation, migration, and invasion of glioma cells." (PMID 40061958, 2025). "In addition, we will investigate the effects of MFAP4 on tumor immune evasion and drug resistance to reveal its mechanisms in gliomas." (PMID 40061958, 2025). "The results of such a dataset suggest that MFAP4 may be a prognostic biomarker for many cancers, including gliomas." (PMID 40061958, 2025). "MFAP4 was significantly elevated in glioma tissues compared to controls." (PMID 40061958, 2025). "MFAP4 was an independent prognostic indicator and significantly correlated with glioma progression." (PMID 40061958, 2025). "MFAP4 levels also correlate with the concentrations of many chemokines and chemokine receptors as well as immune checkpoints in glioma tissues, suggesting that it may influence the tumor microenvironment through multiple mechanisms composition." (PMID 40061958, 2025). "In addition, we correlated MFAP4 with the expression of immunoinhibtors, chemokines, and chemokine receptors in gliomas from The Cancer Genome Atlas (TCGA) dataset." (PMID 40061958, 2025). "Our findings suggest that MFAP4 may play an important role in tumor immunomodulation and may serve as a drug target for glioma." (PMID 40061958, 2025). "MFAP4 may play a key role in specific pathological processes in gliomas or may have a tissue-specific expression pattern, which does not have a similar function in other cancers." (PMID 40061958, 2025). "In conclusion, MFAP4 holds promise as a biomarker and potential therapeutic target in gliomas." (PMID 40061958, 2025). "However, the specific activation mechanism of MFAP4 in gliomas needs to be explored and investigated in deeper experimental areas." (PMID 40061958, 2025). "Evaluating the efficacy of antibodies or small-molecule inhibitors targeting MFAP4 in glioma treatment could provide new therapeutic strategies." (PMID 40061958, 2025). "The DEGs identified between the MFAP4 High and MFAP4 Low groups in gliomas were then examined." (PMID 40061958, 2025). "Thus, MFAP4 may influence glioma progression and prognosis through its ability to regulate ferroptosis." (PMID 40061958, 2025). "Interestingly, MFAP4 is highly expressed only in gliomas and diametrically opposite in other cancers, which may be due to the fact that gliomas are highly heterogeneous tumors whose development involves a variety of molecular mechanisms." (PMID 40061958, 2025).
glioma (continued). "Given the integrative regulatory role of MFAP4 in tumor immunity as well as ferroptosis, therapeutic regimens that block MFAP4 may be a promising strategy for the development of more comprehensive and specific tumor immunotherapy for gliomas." (PMID 40061958, 2025). "The lack of experiments on the relevant regulatory mechanisms has led to the fact that we do not know the specific mechanism of action of MFAP4 in promoting the proliferation, migration and invasion of glioma cells." (PMID 40061958, 2025).
hepatocellular carcinoma (2 papers, 2022 to 2023). A malignant tumor that arises from hepatocytes. "Increased serum MFAP4 was observed in hepatocellular carcinoma patients and MFAP4 was suggested as a potential biomarker in the serous ovarian cancer due to high expression and association with chemoresistance." (PMID 35805199, 2022).
Myocardial fibrosis (2 papers, 2023 to 2024). "Similar to SPON2 and THBS2, in pre-clinical models, myocardial MFAP4 expression appears to protect from myocardial fibrosis and hypertrophy in response to pressure overload or neurohormonal activation." (PMID 38225249, 2024). "Myocardial fibrosis and cardiac remodeling are known as the pathological hallmarks of DCM, and the association of hub genes (MFAP4, ASPN, and FAP) with fibrosis and cardiac remodeling has been identified in prior research." (PMID 37869159, 2023).
myocardial infarction (2 papers, 2013 to 2023). Gross necrosis of the myocardium, as a result of interruption of the blood supply to the area, as in coronary thrombosis. "Although MFAP4 did not confer a role in myocardial infarction (MI) (STEMI + non-STEMI) (p = 0.304), in STEMI patients, declined plasma MFAP4 levels were more common (OR = 0.216, 95% CI 0.070–0.665, p = 0.008)." (PMID 36650606, 2023). "This heterogeneity may possibly provide an explanation for the apparent distribution of serum MFAP4 into two distinct groups in the non-STEMI patients and larger studies with more patients within each category and with more detailed information about the type of myocardial infarction are warranted." (PMID 24349233, 2013).
myocardial ischemia (2 papers, 2013 to 2023). A disorder of cardiac function caused by insufficient blood flow to the muscle tissue of the heart. "With gradually aggravated myocardial ischemia, increased MFAP4 probably help alleviate vascular injury and subsequent atherosclerotic changes, and contribute to neovascularization of ischemic myocardium." (PMID 36650606, 2023). "Therefore, we suggest that the increased MFAP4 levels observed is released from the blood vessel wall into the circulation during myocardial ischemia, leveling out the serum MFAP4 depression in atherosclerotic patients." (PMID 24349233, 2013).
neuroblastoma (2 papers, 2022 to 2023). Neuroblastoma (NB) is the most common solid, extracranial childhood tumor. "MFAP4 is also highly expressed in human neuroblastoma, where it was associated with lower survival rates." (PMID 35805199, 2022). "Furthermore, MFAP4 was identified as a direct target of a tumor-suppressive micro-RNA449a that participates in neuroblastoma cell differentiation." (PMID 35805199, 2022).
Smith-Magenis syndrome (2 papers, 2020 to 2022). Smith-Magenis syndrome (SMS) is a complex genetic disorder characterized by variable intellectual deficit, sleep disturbance, craniofacial and skeletal anomalies, psychiatric disorders, and speech and motor delay. "Genetic studies in humans have implicated MFAP4 in the pathogenesis of Smith-Magenis syndrome, in which patients present with multiple congenital abnormalities and mental retardation, as well as in the severe cardiac malformation left-sided congenital heart disease." (PMID 32678226, 2020). "MFAP4 gene is located on chromosome 17p11.2 and was first described in humans as one of the genes commonly deleted in Smith-Magenis syndrome (SMS), a complex genetic disorder characterized by physical abnormalities and neurobehavioral features." (PMID 35805199, 2022).
type 1 diabetes (2 papers, 2021). "In previous studies, there was a large amount of evidence that MFAP4 directly or indirectly affects the occurrence and development of type 1 diabetes mellitus, but this gene might be novel target for GDM." (PMID 33890634, 2021).
-dependent (1 paper, 2017). "While numerous genes are altered during the development of Ang II-dependent hypertension, only Sphk1, Srpx and Mfap4 were common for different vascular areas studied." (PMID 28276483, 2017).
acute coronary syndrome (1 paper, 2023). Signs and symptoms related to acute ischemia of the myocardium secondary to coronary artery disease. "Microfibrillar-associated protein (MFAP4), initially identified as an extracellular matrix protein, has been demonstrated in multiple human disorders, but it is yet to be discovered following acute coronary syndrome (ACS) in clinical practice." (PMID 36650606, 2023).
biliary atresia (1 paper, 2025). A rare, biliary tract disease characterized by progressive obliterative cholangiopathy of the intra- and extrahepatic bile ducts, occurring in the embryonic/ perinatal period, leading to severe and persistent neonatal jaundice and acholic stool. "MFAP4 via PCR and immunohistochemistry is significantly upregulated in biliary atresia compared to total functional cyst liver tissue." (PMID 40492258, 2025). "RT-qPCR results suggested that both COL1A1 and MFAP4 were significantly upregulated in biliary atresia compared to the total functional cyst liver tissue (P < 0.05)." (PMID 40492258, 2025).
brain tumor (1 paper, 2025). "We also analyzed the dependence of cell lines on MFAP4 in DepMap, and the results suggest that MFAP4 has an important role in brain tumor types and may be a potential therapeutic target." (PMID 40061958, 2025).
congestive heart failure (1 paper, 2016). Failure of the heart to pump a sufficient amount of blood to meet the needs of the body tissues, resulting in tissue congestion and edema. "Yet, in a recent study only congestive heart failure was found to be associated with significantly increased MFAP4 plasma levels." (PMID 27378383, 2016).
coronary artery disease (1 paper, 2023). "When all significant univariate determinants (p < 0.05), including conventional coronary artery disease risk factors like TC, LDL, cTnI, CKMB, were entered into multivariate model, decreased MFAP4 concentration was also an independent determinant of STEMI (OR = 0.395, 95% CI 0.174–0.895, p = 0.026)." (PMID 36650606, 2023).
coronary stenosis (1 paper, 2023). Narrowing of the coronary artery lumen diameter. "Similarly, in our study, the baseline plasma MFAP4 level was negatively associated with coronary stenosis while increased MFAP4 levels prospectively predict the development of MACE in ACS." (PMID 36650606, 2023). "The present study shows that MFAP4 levels were negatively correlated with the severity of coronary stenosis, and specifically low MFAP4 was an independent determinant of STEMI." (PMID 36650606, 2023). "Accordingly, in this study, we aimed to investigate the correlation between severity of coronary stenosis, calculated by coronary angiography, and the circulating MFAP4 levels in a cohort of patients admitted with ACS." (PMID 36650606, 2023). "Therefore, this study aimed to investigate the relationship between circulating MFAP4 levels and coronary stenosis in ACS." (PMID 36650606, 2023). "Contrary to the opposite trend between MFAP4 and coronary stenosis, our study found a significant decrease in asymptomatic survival in the high MFAP4 group, which may suggest that MFAP4 plays different roles in the disease process." (PMID 36650606, 2023). "MFAP4 has a potential as a biomarker for the degree of coronary stenosis in ACS." (PMID 36650606, 2023). "A possible explanation of our present findings of negative relationship between MFAP4 levels and coronary stenosis in ACS may attribute extracellular matrix remodeling during plaque rupture." (PMID 36650606, 2023).
Crohn disease (1 paper, 2024). A gastrointestinal disorder characterized by chronic inflammation involving all layers of the intestinal wall, noncaseating granulomas affecting the intestinal wall and regional lymph nodes, and transmural fibrosis. "When adjusting for confounders for MFAP4 levels, (CID, age, sex, smoking status and BMI), High MFAP4 showed a positive association with treatment outcome in all CIDs except Crohn’s disease, enabling High MFAP4 as a potential biomarker for biological treatment response." (PMID 39465398, 2024). "When considering the CID subgroups except for Crohn ́s disease, being in a High MFAP4 (having a high serum MFAP4 level) predicts a positive treatment response to biologic therapy; however, the subgroups were underpowered for individual analysis, resulting in wide CI’s." (PMID 39465398, 2024).
diabetic neuropathy (1 paper, 2017). A chronic, pathological complication associated with diabetes mellitus, where nerve damages are incurred due to diabetic microvascular injury involving small blood vessels that supply these nerves, resulting in peripheral and/or autonomic nerve dysfunction. "Plasma MFAP4 levels have been associated with various cardiovascular complications and diabetic neuropathy." (PMID 28360945, 2017).
dissection (1 paper, 2019). The separation and isolation of tissues for surgical purposes, or for the analysis or study of their structures. "Plasma TGF-β1 levels associate with aortic root growth and, therefore, may predict prophylactic aortic root surgery to prevent type A dissections, whereas plasma MFAP4 levels seem related to reduced distensibility of the descending aorta and predict the probability of a type B dissection." (PMID 31315432, 2019).
gestational diabetes (1 paper, 2022). Carbohydrate intolerance first diagnosed during pregnancy. "Related findings include differential methylation in cord blood in genes ATP5A1, MFAP4, PRKCH, SLC17A4 related to Gestational Diabetes (GDM); and hypermethylation of the LEP gene promoter associated with maternal obesity on the fetal side of the placenta." (PMID 35749371, 2022).
glioblastoma (1 paper, 2025). The most malignant astrocytic tumor (WHO grade IV). "Many of the identified differentially expressed genes are understudied in glioblastoma; however, several are key regulators of tissue remodeling (MFAP4 and ALX4), mesoderm development (TBX5 and ALX4), and immune modulation (FUT2, C4BPA, MFAP4, and GRM4)." (PMID 41066027, 2025).
injury (1 paper, 2021). Damage inflicted on the body as the direct or indirect result of an external force, with or without disruption of structural continuity. "In terms of interaction with serious complications in COVID‐19 patients, 6 markers (MFAP4, ECM1, CDKN2B.AS1, CAPN2, FGG, and CD147) and 2 exRNAs (SNORD33 and miR‐122‐5p) are involved in thrombosis or liver injury." (PMID 34122778, 2021).
ischemia (1 paper, 2018). A hypoperfusion of the BLOOD through an organ or tissue caused by a PATHOLOGIC CONSTRICTION or obstruction of its BLOOD VESSELS, or an absence of BLOOD CIRCULATION. "A possible explanation of our present observations of the increased level of sMFAP4 in symptomatic PAD patients with the most severe outcomes may be that vascular bed remodeling and/or ischemia causes tissue disruption and release of ECM molecules, including MFAP4, into the circulation." (PMID 29884190, 2018).
liver cancer (1 paper, 2023). An epithelial or non-epithelial malignant neoplasm that arises from the liver. "Even more the knockdown of Mfap4 in human liver cancer cells (HepG2) did not accelerate cell proliferation further." (PMID 37935709, 2023). "Furthermore, knockdown of MFAP4 in human liver cancer cells does not accelerate their proliferation further and knockdown of Mfap4 in immortalized, sensitized hepatocytes did not transform these cells." (PMID 37935709, 2023).
oral squamous cell carcinoma (1 paper, 2022). "In oral squamous cell carcinoma, MFAP4 expression was significantly decreased, while high MFAP4 was associated with better prognosis." (PMID 35805199, 2022).
pancreatic adenocarcinoma (1 paper, 2025). "Notably, in pancreatic adenocarcinoma, MFAP4 was identified as a carrier of sialyl-Lewis x with significantly higher expression compared to control tissues." (PMID 39822989, 2025).
pancreatic ductal adenocarcinoma (1 paper, 2022). An infiltrating adenocarcinoma that arises from the epithelial cells of the pancreas. "Increased MFAP4 expression was observed in the pancreatic ductal adenocarcinoma (PDA) stroma, with MFAP4 identified as a carrier of the tumor-associated carbohydrate sialyl-Lewis x, suggesting this MFAP4 glycoform as a potential PDA biomarker." (PMID 35805199, 2022).
Potocki-Lupski syndrome (1 paper, 2012). "Another example, MFAP4, is located within the Smith-Magenis/Potocki-Lupski syndrome region, thought to be an elastin-binding matrix protein involved in cell adhesion and highly expressed in developing valves and great vessels." (PMID 22969434, 2012).
prostate tumor (1 paper, 2019). "In aggressive prostate tumor tissues, the co-regulation of cathepsin L and a variety of extracellular membrane (ECM) proteins, such as periostin and MFAP4 (Microfibrillar-associated protein-4), was observed." (PMID 31412618, 2019).
sarcoma (1 paper, 2025). A usually aggressive malignant neoplasm of the soft tissue or bone. "While previously reported as pro-tumorigenic in some sarcomas, our findings unequivocally position MFAP4 as a tumor suppressor in TNBC." (PMID 41451212, 2025).
schizophrenia (1 paper, 2012). A major psychotic disorder characterized by abnormalities in the perception or expression of reality. "To date, we are the first to report downregulation of MFAP4 in schizophrenia." (PMID 22441714, 2012).
steatosis (1 paper, 2023). Increased lipid within the cytoplasm of cells. "Based on the macrovesicular steatosis score given by the certified pathologist in a blinded scoring, there is a reduction in the case of Mfap4 knockdown." (PMID 37935709, 2023).